TYK2 (tyrosine kinase 2)
Diseases named in the same sentence as TYK2 in open-access papers (continued):
Sharing a sentence is not in itself a finding about the gene and the disease.
cancer (continued). "While activating mutations in other members of the JAK family have long been known to be tumorigenic, it has only been in the last 10 years that a series of screening studies have shown the involvement of TYK2 as an oncogene driving cancer development and metastases." (PMID 34439323, 2021). "Additionally, a protein chaperone, heat-shock protein 90 (HSP90), has been shown to interact with and stabilize TYK2 and other JAKs in cancer cells, and thus is a promising therapeutic target." (PMID 34439323, 2021). "Originally known for its immune modulatory role, TYK2 is now emerging as an oncogene that could serve as both a prognostic biomarker and a promising drug target in cancer." (PMID 34439323, 2021). "TYK2 signals to stimulate proliferation and metastasis while inhibiting apoptosis of cancer cells." (PMID 34439323, 2021). "Here, we highlight the latest findings on the consequences of TYK2 hyperactivity in cancer cells." (PMID 31694222, 2019). "Since biological effects of IFN-α and IFN-γ are both mediated by Jak1, it appeared that Tyk2 tyrosine kinase or the receptor may be impaired in IFN-α resistant carcinoma cells upstream of STAT1." (PMID 11875714, 2002). "However, it remains unclear how cancer cell-specific Tyk2 deletion can lead to increased IFN signaling as seen in Tyk2ΔIEC tumors." (PMID 36185806, 2022). "TYK2 is reported to be overexpressed in the prostate, ovarian, cervical, and breast cancers." (PMID 35646067, 2022). "Deletion of Tyk2 in Paneth-like cancer might change Jak-Stat signaling in a cell-intrinsic manner." (PMID 36185806, 2022). "Furthermore, TYK2 mRNA was also up-regulated in other 22 kinds of cancers." (PMID 33731185, 2021). "However, in the light of the findings in this paper and other recent reports, it appears that TYK2 inhibitors may eventually have roles in anti-cancer treatment." (PMID 30131584, 2019). "However, the effects of TYK2 inhibition on cancer development remain unclear." (PMID 40991399, 2026). "However, whether TYK2 inhibitors increases cancer risk has not been extensively evaluated given lack of long-term RCTs." (PMID 36842216, 2023). "For example, STAT5 Y694 and TYK2 Y1054/Y1055 were higher in HER2+ cancers (red arrows), whereas PD1/PDL1 expression levels were high in TN cancers (blue arrows)." (PMID 38086377, 2023). "Tyrosine kinase 2 (TYK2), a member of the Janus kinase (JAK) family, has emerged as both a promising biomarker and a target for anti-cancer therapies." (PMID 35938006, 2022). "The major oncogenic actions of TYK2 are mediated through STAT1, STAT3, and STAT5, and drugs targeting STATs are in development for cancer therapeutics." (PMID 34439323, 2021). "In cancer databases, LOF or lowered TYK2 levels are generally correlated with poor prognosis, while high TYK2 levels are associated with tumorigenesis." (PMID 31936322, 2020). "The current literature regarding deactivation of TYK2 by SOCS1/3, the PTPs PTB1B and SHP1, as well as the global impact of SOCS and PTP family members in cancer are reviewed elsewhere." (PMID 31694222, 2019). "In an ovarian cancer cell line pY-STAT3 co-localizes with TYK2 and JAK2 at focal adhesions, and hyperactive STAT3 was shown to promote cancer cell motility." (PMID 31694222, 2019). "Therefore, any stimulus which deregulates the expression of either JAK1 or TYK2 could potentially deregulate the entire type I IFN response signalling pathway and thereby weaken the immune system and thus predispose individuals to infections and or cancer." (PMID 28344639, 2017). "Evaluation of the effects of Tyk2 deletion in different subsets of immune cells and in CRC cells demonstrated that TYK2 was not required in cancer cells, macrophages, NK cells, T cells, or Kupffer cells." (PMID 40991399, 2026). "These analyses confirmed similar metastatic burden of host mice with AKP and AKPT organoids, suggesting that TYK2 has no cancer-intrinsic function in this CRLM model." (PMID 40991399, 2026).
cancer (continued). "At that time, the TYK2 mRNA transcript was detected only in colorectal polyps, with no trace of its expression in cancer." (PMID 39518103, 2024). "DEFB1 and TYK2 protein expression did not match the intergroup differences between cancer and adjacent normal tissues in the transcriptome." (PMID 38375157, 2024). "TYK2 expression was significantly higher for cancers not exceeding 2 cm in diameter than for large lesions (p = 0.0309, Mann–Whitney U test)." (PMID 39518103, 2024). "Dysregulated activation of TYK2 in cancers may lead to hyperactive JAK/STATs signal, which may play an important role in the occurrence and development of cancers." (PMID 37237254, 2023). "To evaluate if IST5 affects kinase activity in cancer cells, we tested kinase inhibitory activity of IST5 in two custom-tailored panels including 54 relevant kinases, including Jak1, Jak2, Jak3, Tyk2, Abl1, Abl2, Lck, Fyn, Src and TrkB/C." (PMID 33217941, 2020). "Collectively, these findings indicate that the inhibitory effect of IST5 on Stat5 phosphorylation in cancer cells is not due to inhibition of Jak2 or other key kinases including Jak1, Jak3, Tyk2, Src, Lck, Fyn, TrkB/C, Abl1 or Abl2." (PMID 33217941, 2020). "Taken together, these data illustrate the importance of TYK2 in MPNST pathogenesis and suggest that the TYK2 pathway may be a potential therapeutic target for these deadly cancers." (PMID 31278855, 2019). "Notably, this study solely genotyped the somatic cancer cells and overlooked that this mutation impairs TYK2 catalytic activity; cellular signaling, however, is not completely abrogated, and the detected induction of BCL2 expression might favor an anti-apoptotic program." (PMID 31694222, 2019). "The activated JAK1 and TYK2 in turn phosphorylate STAT1 and STAT2 setting in motion a cascade of events which finally initiates the transcription of IFN-inducible genes switching on the anti-cancer and anti-viral effects as reviewed in Randall and Goodbourn." (PMID 28344639, 2017). "However, no mutations were identified in the cancer hotspot locations of IL23R, IL12Rß1, IL12Rß2, OSMR, TYK2, and JAK2 across all mutant distributions." (PMID 36232773, 2022). "Another interesting protein non-receptor tyrosine protein kinase TYK2 (TYK2) has been reported as overexpressed in prostate, ovarian, cervical, and breast cancers." (PMID 35646067, 2022). "In light of these findings we hypothesize that TYK2 and other JAKs are important modulators of FGF-2-driven cell survival and that inhibitors of these kinases will likely improve the effectiveness of other cancer therapies." (PMID 21625473, 2011). "Collectively, our data suggest that TYK2, JAK1 and JAK2 are novel targets that may prove useful to circumvent drug resistance mediated by FGF-2, a growth factor often secreted by cancer cells, or their supporting tissues, and elevated in cancer patients." (PMID 21625473, 2011).
bacterial infections (6 papers, 2013 to 2024). "Mice deficient in TYK2 for example have been shown to be susceptible to overwhelming viral and bacterial infections." (PMID 23527226, 2013). "Among the JAK family members, TYK2 holds significance in mediating IL-10 dependent signaling as anti-inflammatory responses during bacterial infections." (PMID 37808912, 2023). "Two other patients with nonsense TYK2 mutations displayed characteristics of HIES, but did not experience significant viral or bacterial infections." (PMID 34439323, 2021).
infectious disease (5 papers, 2018 to 2025). A disorder directly resulting from the presence and activity of a microbial, viral, or parasitic agent in humans. "Here, we investigate the history of human exposure to TB by determining the evolutionary trajectory of the TYK2 P1104A variant in Europe, where TB is considered to be the deadliest documented infectious disease." (PMID 33667394, 2021). "Moreover, TYK2 P1104A does not affect the risk for other infectious diseases except, to a milder degree, rare cases of infection by environmental mycobacteria in otherwise healthy individuals." (PMID 33667394, 2021).
hematologic malignancies (4 papers, 2012 to 2025). "The JAK family includes JAK1, JAK2, JAK3, and Tyk2, and their inhibition is known to be therapeutic for many autoimmune and hematological diseases." (PMID 39742289, 2024).
Hematological Cancers (3 papers, 2019 to 2025). "In a proteomics screen for tyrosine kinase variants, multiple brain and hematopoietic cancer cell lines harbored an inactivating TYK2 splice variant, E971fsX67." (PMID 34439323, 2021). "A prominent germline TYK2 mutation is P1104A/V, which was first found to be associated with solid and hematopoietic cancers and later with immunological and inflammatory disorders." (PMID 31694222, 2019). "Additionally, four TYK2 fusion proteins have been identified in several hematologic cancers using genomic and transcriptomic sequencing." (PMID 34439323, 2021).
hematological neoplasm (3 papers, 2019 to 2023). "TYK2 is associated with the fewest hematological neoplasm variants overall and is more commonly associated with inflammatory disorders." (PMID 37834019, 2023).
adenocarcinoma (2 papers, 2024 to 2025). A common cancer characterized by the presence of malignant glandular cells. "Considering that early diagnosis is key in CRC therapy, our results support the use of TYK2 in the assessment of colonic biopsies to monitor the risk of progression to adenocarcinoma, and CACC in particular." (PMID 39518103, 2024). "Further research should include comparative analyses of adenocarcinomas with polyps and assess blood or plasma TYK2 levels to define the overall potential of this tyrosine kinase for use in the early detection of CRC." (PMID 39518103, 2024). "TYK2 expression was not greater in adenocarcinomas of the mucous subtype than in other histological subtypes of CRC (p = 0.5704, Mann Whitney test)." (PMID 39518103, 2024). "Our analyses did not allow us to deduce whether the expression level of TYK2 allows for the differential diagnosis of adenocarcinomas of extraintestinal origin." (PMID 39518103, 2024).
gastrointestinal disorders (1 paper, 2022). "TYK2 has lately gained attention as a potential therapeutic for IBD; its connection to gastrointestinal disorders has long been established." (PMID 36232773, 2022).
inflammation (1 paper, 2017). Aberrant reaction of the microcirculation characterized by movement of fluid and leukocytes from the blood into extravascular tissues. "TYK2 rs280519 showed the stronger association with NIA grade: while the A/A genotype was present in near 30% of the patients with moderate NIA, only 8% of the patients with severe liver inflammation carried this genotype (p = 0.009)." (PMID 28704535, 2017).
intestinal disease (1 paper, 2025). "In essence, the blockade of IL‐10 by JAKi, especially Tyk2 inhibition, may lead to a differential effect of therapy across SpA spectrum joint and intestinal disease." (PMID 40320905, 2025).
TYK2 also shares sentences with these, for which no sentence is quoted: alopecia areata (4 papers); primary biliary cirrhosis (4); viral diseases (4); ankylosing spondylitis (3); osteosarcoma (3); acne (2); arthropathy (2); Cognitive impairment (2); dyslipidemia (2); enthesitis (2); experimental autoimmune encephalomyelitis (2); hepatic cancer (2); immunodeficiency 35 (2); Insulin resistance (2); intestinal inflammation (2); lichen planus (2); neuroblastoma (2); non-Hodgkin lymphoma (2); respiratory diseases (2); Splenomegaly (2); allergies (1); alopecia (1); autoimmune hypothyroidism (1); autoimmune lymphoproliferative syndrome (1); autoimmune polyendocrinopathy (1); autoimmune type 1 diabetes (1); Burkitt lymphoma (1); cardiomyopathy (1); cardiovascular diseases (1); cellulitis (1).
A further 71 diseases each share a sentence with TYK2 in 1 paper.